PCSK9 (proprotein convertase subtilisin/kexin type 9)
Diseases named in the same sentence as PCSK9 in open-access papers (continued):
Sharing a sentence is not in itself a finding about the gene and the disease.
dyslipidemia (continued). "Thyroid hormone administration possibly also sustains and enhances the efficacy of hypolipidemic drugs, such as statins, ezetimibe and proprotein convertase subtilisin/kexin type 9 (PCSK9), in patients with dyslipidemia and hypothyroidism." (PMID 30233497, 2018). "The discovery of proprotein convertase subtilisin/kexin type 9 (PCSK9) has created a new frontier for better management of dyslipidemia." (PMID 29562587, 2018). "Third, we evaluated the discordances of PCSK9, apoC3, and sdLDL-C with current dyslipidemias, and found substantial discordances exist in each dylipidemia group and normalipidemia patients." (PMID 27713142, 2017). "In conclusion, PCSK9, apoC3, and sdLDL-C showed significant interactions with current dyslipidemias, and were predictive in the screening." (PMID 27713142, 2017). "Patients with a history of metabolic syndrome had smaller changes in PCSK9 concentrations than other patients." (PMID 29296222, 2017). "This is a very exciting period in the field of dyslipidemia, where thanks to new PCSK9-silencing therapies, LDLc levels were lowered to unprecedented levels, reaching almost 0.4 mM." (PMID 28971102, 2017). "PCSK9, apoC3, and sdLDL-C showed significant interactions with current dyslipidemias, and were predictive in the screening." (PMID 27713142, 2017). "The recent development of the plasma proprotein convertase subtilisin/kexin type 9 (PCSK9) inhibitors has highlighted the importance of PCSK9 as a new therapeutic target for lowering LDL-C and dyslipidemia-associated CV disease (CVD)." (PMID 28704936, 2017). "The future will tell which strategies targeting PCSK9, other than mAbs, will find their way in dyslipidemia and cardiology clinics throughout the world and result in affordable and safe treatments." (PMID 28971102, 2017). "Despite the interactions, a high degree of discordances of PCSK9, apoC3, and sdLDL-C with current dyslipidemias were detected." (PMID 27713142, 2017). "In polytomous logistic regression models, we analyzed the interactions of the elevated PCSK9, apoC3, and sdLDL-C levels with increasing dyslipidemias." (PMID 27713142, 2017). "Findings from this study suggest that exercise training protects against diet-induced dyslipidemia and differentially modulates the hepatic expression and circulating concentrations of PCSK9." (PMID 23862065, 2013). "Further studies will be required to gain insight into the role of PCSK9 in the dyslipidemia that accompanies infections and chronic inflammatory diseases, such as periodontitis." (PMID 22992388, 2012). "In pregnant women, PCSK9 levels were significantly higher in the gestational diabetes mellitus (GDM) group than those with standard glucose tolerance (NGT), suggesting a possible pathophysiological role for PCSK9 in GDM-related dyslipidemia and glycemic dysregulation." (PMID 41008547, 2025). "The interplay among OS, dyslipidemia, IR, hormonal imbalance, and external exposures may collectively shape PCSK9 expression patterns in affected women." (PMID 41516208, 2025). "PCSK9 inhibitors are effective therapeutics to treat dyslipidemia, by reducing the LDL-C." (PMID 40006605, 2025). "In contrast, vaccines have been developed to induce PCSK9-specific antibodies, which could improve dyslipidemia in atherosclerotic animal models." (PMID 41346351, 2025). "PCSK9 inhibitors are therefore recommended for managing dyslipidemia." (PMID 39445733, 2025). "Lipid levels appeared to be lower after treatment with PCSK9 inhibitors, indicating that this type of dyslipidemia treatment may be a safe choice for managing the cardiovascular risk in these patients." (PMID 40249406, 2025).
dyslipidemia (continued). "The phase 3 Clinical Research of Developing PCSK9 Inhibitor as Cholesterol-Lowering Therapy in Chinese Patients with Dyslipidemia-1 (CREDIT-1) study showed that tafolecimab was safe and exhibited superior lipid-lowering efficacy compared to the placebo in non-FH patients." (PMID 38543075, 2024). "Therefore, patients suffering from carotid artery disease and dyslipidemia unresponsive to conventional lipid-lowering therapy with statins/ezetimibe should be considered for additional use of PCSK9 inhibitor drugs." (PMID 39099701, 2024). "Commonly prescribed lipid-lowering drugs, such as 3-hydroxy-3-methyl-glutaryl-coenzyme A reductase (HMGCR) inhibitors and proprotein convertase subtilisin/kexin type 9 (PCSK9) inhibitors, play pivotal roles in managing dyslipidemia and reducing cardiovascular risk." (PMID 38623319, 2024). "The recent emergence of PCSK9 inhibitors for the management of dyslipidemia and the more extensive lipid lowering provided by these agents may provide better prevention for ACS patients when initiated after the ACS event." (PMID 39274253, 2024). "Patients with dyslipidemia and newly prescribed statins (n = 865,732), ezetimibe (n = 34,490), or anti-proprotein convertase subtilisin/kexin type 9 monoclonal antibodies (anti-PCSK9 mAbs; n = 1940) were included." (PMID 37603070, 2024). "Additionally, Ongoing research is exploring the use of PCSK9 inhibitors in various patient populations, including those with diabetes, chronic kidney disease, and refractory dyslipidemia." (PMID 39650150, 2024). "Notably, increased PCSK9 expression correlates with CKD-related dyslipidemia, with emerging research suggesting a possible connection between PCSK9 and the immune function." (PMID 38510702, 2024). "Our study observed regional disparities in the utilization of PCSK9 inhibitors that were not correlated with the prevalence of dyslipidemia but were associated with per capita disposable income." (PMID 38840134, 2024). "Initial data from investigations of PCSK9 inhibition in humans indicate that PCSK9 inhibition may be a promising novel therapeutic alternative for the treatment of dyslipidemia and related cardiovascular diseases." (PMID 37055467, 2023). "Increased PCSK9 expression induced by dyslipidemia inhibited SHBG synthesis in the liver, which indicated that PCSK9 may be the core of obesity-related abnormal T synthesis." (PMID 37935689, 2023). "At present, the reason for the higher mortality rate in the group with high PCSK9-Ab titers remains unclear; however, this could be related to past dyslipidemia and platelet function." (PMID 37012310, 2023). "Neutrophil gelatinase-associated lipocalin (NGAL) may promote development of inflammation in psoriasis, whereas proprotein convertase subtilisin/kexin type 9 (PCSK9) may account for dyslipidemia in some psoriatic patients." (PMID 37763277, 2023). "By combining statins or PCSK9 inhibitors with bile acid sequestrants treatment affecting bile acid and cholesterol absorption, optimal management of dyslipidemia may potentially be achieved." (PMID 37627820, 2023). "Therefore, inhibition of PCSK9 is a promising new way to improve dyslipidemia in patients with T2DM to prevent cardiovascular disease." (PMID 36936164, 2023). "Literature has shown that glucose, BP and PCSK9 are some parameters that may be used to describe metabolic syndrome." (PMID 37299433, 2023). "However, LOF genetic variants became the prototype for the creation of a generation of targeted PCSK9 therapy drugs, which showed unprecedented efficacy in treating dyslipidemia both in CAD and in CAD with T2DM." (PMID 38028979, 2023). "A marked increase of circulating PCSK9 observed previously after acitretin therapy may partially explain pharmacologically induced dyslipidemia in patients receiving the drug." (PMID 37763277, 2023).
dyslipidemia (continued). "In addition, we also listed several novel identified modulatory biomarkers which play an important role in the regulation of dyslipidemia induced by hypothyroidism, including PCSK9, ANGPTL3, ANGPTL8, FGF-21, FGF-19, and several microRNAs." (PMID 34784265, 2022). "Previous data observed that PCSK9 levels were increased in type 2 diabetes mellitus/metabolic syndrome patients and positive correlations of PCSK9 levels with LDL, fasting plasma glucose (FPG), glycosylated hemoglobin (HbA1c), fasting insulin, and insulin resistance." (PMID 35498417, 2022). "The treatment of dyslipidemia is dominated by statins, used as monotherapy or in combination with ezetimibe, proprotein convertase subtilisin/kexin type 9 (PCSK9) inhibitors, and fibrates, which have been demonstrated to be effective in lipid-lowering and cardiovascular risk reduction." (PMID 35722157, 2022). "Consequently, clinicians can use PCSK9 inhibitors alone or in combination with statins to manage dyslipidemia." (PMID 36035406, 2022). "In agreement with the 2019 ESC/EAS guidelines for the management of dyslipidemias and the national PCSK9-i prescriptive regulation, PCSK9-i treatment was started in all FH subjects; specifically, six subjects added alirocumab 150 mg and 25 subjects added evolocumab 140 mg, every 2 weeks." (PMID 35928226, 2022). "Thirdly, the current evidence on PCSK9 editing opens the stage for other genetically validated treatment targets in dyslipidemia such as lipoprotein(a), angiopoietin-like 3, and apolipoprotein CIII which can already be silenced with antisense-oligonucleotides and siRNA." (PMID 35050192, 2022). "By this method, PCSK9 could modulate the clearance progression of LDL-C which disrupts the serum cholesterol homeostasis and induces the pathogenic development of dyslipidemia." (PMID 34784265, 2022). "In the present study, we found that subjects with higher circulating PCSK9 had progressively worse cardiometabolic risk profiles in women, including incident high LDL-cholesterol, elevated triglycerides, hypertension, type 2 diabetes, and metabolic syndrome." (PMID 34041285, 2021). "As CKD patients remain a population with unmet needs in the management of dyslipidemia and cardiovascular morbidity and mortality, PCSK9 might be an interesting therapeutic target for the treatment of atherosclerotic disease beyond LDL-C regulation." (PMID 34336112, 2021). "PCSK9 is suggested to be involved in the dyslipidemia and proteinuria of nephrotic syndrome in CKD." (PMID 34336112, 2021). "This evidence indicates that PCSK9 might be a key regulator in lipid metabolism of macrophages, but the effect of PCSK9 on HHcy-induced dyslipidemia is rarely reported." (PMID 34660746, 2021). "Those with mixed dyslipidemia may benefit from polytherapy from the addition of drugs such as ezetimibe, bile acid sequestrants, proprotein convertase subtilisin/kexin type 9 (PCSK9) inhibitors, or adenosine triphosphate-citrate lyase inhibitors." (PMID 34722051, 2021).
dyslipidemia (continued). "The identification of point mutant forms of PCSK9 selectively defective for LDL association, such as A44P, provides important molecular tools to further test this hypothesis in animal models of dyslipidemia." (PMID 31949048, 2020). "PCSK9 seems to be a novel marker of psoriasis and a putative explanation of lipid disturbances, which are common in patients with psoriasis and are vital for the further developing of metabolic syndrome." (PMID 32225075, 2020). "It has been suggested that PCSK9 expression may be driven by insulin resistance, a common feature of metabolic syndrome." (PMID 33302966, 2020). "Presumably, connecting antipsoriatic treatment additionally with other lowering PCSK9 medications could be useful, especially when acitretin is used as a systemic drug in obese psoriatic patients with metabolic syndrome." (PMID 32225075, 2020). "In another study, an anti-PCSK9 (proprotein convertase subtilisin/kexin type 9) peptide vaccine using KLH as the carrier protein was shown to produce long-lasting anti-PCSK9 antibodies and is considered to be the primary vaccine for the treatment of dyslipidemia in the future." (PMID 30656066, 2019). "Here, we aimed to develop vaccine for a long-term treatment of dyslipidemia targeted to PCSK9." (PMID 29438441, 2018). "Recently, the proprotein convertase subtilisin/kexin type 9 (PCSK9) inhibitor evolocumab, which is a therapeutic agent with a new mechanism for dyslipidemia, became available in Japan, and it has been shown to decrease LDL more effectively than other available agents." (PMID 28683788, 2017). "Substantial discordances with PCSK9, apoC3, and sdLDL-C in each dyslipidemia group were observed." (PMID 27713142, 2017). "Plasma CETP activity and PCSK9 levels were measured in 450 participants (median age, 58 years; 49 % women) who attended the metabolism unit because of metabolic syndrome (MetS) (78 %), atherogenic dyslipidemia (32 %), obesity (50 %), type 2 diabetes mellitus (72 %), and other risk factors (13 %)." (PMID 27488210, 2016). "Another protein related to dyslipidemia is proprotein convertase subtilisin/kexin type 9 (PCSK9)." (PMID 24319689, 2013). "Interestingly, regulation of hepatic LDL receptors by resistin involves the related PCSK family member PCSK9, recently identified as a novel target in patients suffering from severe dyslipidemia." (PMID 23936445, 2013). "The primary objective of the PERI-DYS study was to compare the target goal attainment in LDL-C values and general differences in patient characteristics in two cohorts of dyslipidemia patients at very high CV risk: those receiving PCSK9-mAb and those eligible but not receiving these inhibitors." (PMID 40760109, 2026). "Consequently, assessing PCSK9 concentrations in women with PCOS may provide valuable insights into the interplay between dyslipidemia, IR, androgen excess, and related metabolic disturbances." (PMID 41516208, 2025). "In addition to dyslipidemia, PCSK9 may thus be a potential therapeutic target for various pro-inflammatory diseases." (PMID 39149582, 2024). "With the birth of PCSK9 and clinical practice, more and more studies are focusing on patients achieving optimal LDL-C levels and finding that residual cardiovascular risk will be increased if these patients have combined dyslipidemia, particularly for low HDL-C concentrations and high TG levels." (PMID 38566225, 2024). "Indeed, this pilot study could open the way for new research on the PCSK9 role in dyslipidemias and vascular functions." (PMID 35454151, 2022).
dyslipidemia (continued). "On the other hand, several novel identified modulatory biomarkers, such as proprotein convertase subtilisin/kexin type 9 (PCSK9), angiopoietin-like protein (ANGPTLs), and fibroblast growth factors (FGFs), might play an important role in the regulation of dyslipidemia induced by hypothyroidism." (PMID 34784265, 2022). "Thus, there is promising data to suggest that cancer patients with dyslipidemia may benefit from traditional treatment with statins or PCSK-9 inhibitors." (PMID 36017084, 2022). "The reason that the PCSK9 level is associated with dyslipidemia in our study is not elucidated and could be explained by genetic or environmental factors." (PMID 34270402, 2021). "Finally, in patients with stable CVD, low PCSK9 plasma levels were associated with a metabolic pattern characterized by low HDL cholesterol, the metabolic syndrome, elevated BMI, insulin resistance and diabetes with diffuse non-obstructive coronary atherosclerosis." (PMID 33143700, 2020). "Thus, anti-PCSK9 vaccine could become a new option for the treatment of dyslipidemia as a long-acting therapy in future." (PMID 29438441, 2018). "Therefore, anti-PCSK9 vaccination may be an innovative approach and may provide a new therapeutic option for the treatment of dyslipidemia." (PMID 29438441, 2018). "Furthermore, discordances of PCSK9, apoC3, and sdLDL-C with current dyslipidemias were observed." (PMID 27713142, 2017). "Therefore, PCSK9 has been considered as an important novel target for controlling dyslipidemia." (PMID 25889684, 2015). "Therefore, it is reasonable to deduce that patients with dyslipidemia may get more benefits from PCSK9 inhibitors, such as monoclonal antibody, if it be used before the application of lipid-lowering drugs in clinical practice." (PMID 24533584, 2014). "RNA-based therapies targeting PCSK9, Lp(a), ApoC-III, and ANGPTL3 hold transformative potential for treating dyslipidemia effectively." (PMID 39940794, 2025). "In a Phase IIb trial (NCT04641299), a single subcutaneous dose of 90 mg AZD8233 effectively reduced PCSK9 by more than 90%, with a maximum average reduction of nearly 70% in LDL-C levels in patients with dyslipidemia." (PMID 40006605, 2025). "Assuming 5% liver bioavailability in humans, an oral dosage of 15 mg per day is expected to reduce PCSK9 by 80% in a steady state, which supports the development of an oral dosage form of PCSK9 ASO for the treatment of dyslipidemia." (PMID 40006605, 2025). "Although this could partially explain the association between the PCSK9 concentration and dyslipidemia found in our study, this fact does not justify the association with the presence of hyperTG because none of the patients were receiving treatment with fibrates." (PMID 38532033, 2024). "In recent years, the advent of novel therapeutic agents, such as proprotein convertase subtilisin/kexin type 9 (PCSK9) inhibitors, has provided promising avenues for effectively managing dyslipidemia." (PMID 39452487, 2024). "Recently published results of the GOULD registry on the management of dyslipidemia of ASCVD patients from the United States found ∼10% of patients stated an LDL‐C treatment goal <70 mg/dl, ∼25% in the group treated with a PCSK9‐inhibitor." (PMID 36448416, 2023). "In addition, several newly identified modulatory biomarkers, such as proprotein convertase subtilisin/kexin type 9, angiopoietin-like protein, and fibroblast growth factors, might play an important role in the regulation of dyslipidemia induced by hypothyroidism." (PMID 34784265, 2022). "Leptin particulates in cholesterol-regulating functions via proprotein convertase subtilisin/kexin type 9 pathway and down-regulates expression of LDL receptors in hepatocytes, leading to elevated plasma LDL-C levels and dyslipidemia." (PMID 33667284, 2021). "An emerging class of drugs for the management of dyslipidemias and the reduction of CVR is represented by the PCSK9 inhibitors." (PMID 34209552, 2021).